MSN (moesin)
Diseases named in the same sentence as MSN in open-access papers (continued):
Sharing a sentence is not in itself a finding about the gene and the disease.
pancreatic adenocarcinoma (1 paper, 2011). "Moesin-positive cases of pancreatic adenocarcinoma have been associated with shorter survival times than moesin-negative cases, with moesin-positive tumors demonstrating higher histopathologic grades and perineural and lymphovascular invasion rates." (PMID 21235778, 2011). "The finding that moesin appears to be down regulated from Stage 2 to Stage 4 may seem counterintuitive, as moesin-positive tumors have been shown to demonstrate higher perineural invasion rates in pancreatic adenocarcinoma." (PMID 21235778, 2011).
pancreatitis (1 paper, 2025). Inflammation of the pancreas.
papilloma (1 paper, 2016). A benign epithelial neoplasm that projects above the surrounding epithelial surface and consists of villous or arborescent outgrowths of fibrovascular stroma. "We noted relatively decreased apical plasma membrane staining of NHERF1 and moesin in papilloma." (PMID 27229317, 2016). "The subcellular localization of moesin, ezrin and NF2 in CP papilloma was similar to that from normal CP." (PMID 27229317, 2016).
periodontal diseases (1 paper, 2022). "Thus, moesin may play an important role in innate immune responses and TLR4-mediated pattern recognition in periodontal diseases." (PMID 36119109, 2022).
periodontitis (1 paper, 2022). An acute or chronic inflammatory process that affects the tissues that surround and support the teeth. "Since dental status suggests severe periodontitis, and moesin is involved in several innate and adaptive immune functions, moesin dysfunction may be indirectly linked to tooth loss." (PMID 36119109, 2022).
psoriasis (1 paper, 2014). An autoimmune condition characterized by red, well-delineated plaques with silvery scales that are usually on the extensor surfaces and scalp. "In this study, a total of 22 psoriasis-associated autoantigens, including moesin, K17, STIP1, and ANXA1, were identified employing 2D-IB with sera from patients with psoriasis." (PMID 25010044, 2014). "The serum levels of moesin were detected by dot blot analysis in sera from psoriasis patients and healthy controls." (PMID 25010044, 2014). "Thus, moesin may have a crucial role in the pathogenesis of psoriasis." (PMID 25010044, 2014). "In this study, we analyzed serum levels of moesin, K17, STIP1, and ANXA1 in psoriasis patients and healthy controls, and measured the stainability of these proteins in psoriasis tissues." (PMID 25010044, 2014). "Furthermore, serum levels of moesin, keratin 17 (K17), annexin A1 (ANXA1), and stress-induced phophoprotein-1 (STIP1), which were detected as autoantigens, were studied by dot blot analysis with psoriasis patients and healthy controls." (PMID 25010044, 2014). "The STIP1 or moesin, CK17 serum level was not correlated with disease activity of psoriasis patients." (PMID 25010044, 2014).
psoriasis vulgaris (1 paper, 2014). Plaque psoriasis is the most common presentation of psoriasis. "Two proteins each, moesin and K17 for psoriasis vulgaris, and STIP1 and ANXA1 for psoriatic arthritis, were selected for further experiments, because the expression levels of these proteins were more than twice those in healthy controls." (PMID 25010044, 2014). "Our results suggest that moesin and STIP1 may be useful sero-diagnostic markers for psoriasis vulgaris and psoriatic arthritis." (PMID 25010044, 2014). "The levels of moesin and STIP1 were significantly higher in sera from patients with psoriasis vulgaris than in the controls (moesin: P<0.05, STIP1: P<0.005)." (PMID 25010044, 2014). "Moesin expression was observed in the upper stratum spinosum and basal layer in the epidermis of 28 of 34 of psoriatic skin samples, including psoriasis vulgaris and psoriatic arthritis, but was negative in 16 controls except one." (PMID 25010044, 2014). "However, the serum STIP1 or moesin, CK17 level was not correlated with PASI score or BSA in patients with psoriasis vulgaris or psoriatic arthritis and DAS28 or BASDAI swollen or tender joint counts, and involved joint counts in patients with psoriatic arthritis." (PMID 25010044, 2014).
psoriatic arthritis (1 paper, 2014). Joint inflammation associated with psoriasis. "Also the serum STIP1 or moesin, CK17, ANXA1 level was not correlated with DAS28 or BASDAI in patients with psoriatic arthritis." (PMID 25010044, 2014).
renal cell carcinoma (1 paper, 2021). "Considering the association of TMIGD1 with moesin, we decided to investigate whether TMIGD1 expression in renal cell carcinoma, 786-0 cell line could modulate microtubule stability." (PMID 34503512, 2021). "Having established a functional link between TMIGD1 and moesin, we asked whether expression profiles of the TMIGD1 and ERM family proteins, moesin and ezrin, correlate with survival of renal cell carcinoma (RCC) patients." (PMID 34503512, 2021).
retinitis pigmentosa (1 paper, 2023). Retinitis pigmentosa (RP) is an inherited retinal dystrophy leading to progressive loss of the photoreceptors and retinal pigment epithelium and resulting in blindness usually after several decades. "Their phenotypes were difficult to distinguish from other forms of hereditary retinopathies, in whom three with MSN nonsense variants showed phenotypes mimicking FEVR, while the remaining three had performances resembling retinitis pigmentosa." (PMID 37711606, 2023).
rheumatic diseases (1 paper, 2024). "Moesin is also involved in immune cell activation and cell polarity maintenance, possibly contributing to the pathogenesis of rheumatic diseases." (PMID 38267973, 2024). "Herein, about half of the patients with OCLDs have been diagnosed with rheumatic diseases such as SS, RA, AAV, SLE, etc., in which studies have found that moesin may serve as a novel autoantigen." (PMID 38267973, 2024).
schwannoma (1 paper, 2025). A benign, usually encapsulated slow growing tumor composed of Schwann cells. "It is now unanimously accepted in the literature that the origin of schwannomas is associated with a mutation in a cytoskeletal protein called Merlin, Neurofibromin 2, or schwannomin, which belongs to the ERM (Ezrin–Radixin–Moesin) protein family and is regulated by the tumor suppressor gene NF2." (PMID 40722574, 2025).
Secretory Meningioma (1 paper, 2018). A WHO grade I meningioma characterized by the presence of epithelial differentiation and numerous intracellular PAS positive bodies that are rich in glycogen. "As in secretory meningioma, moesin but not NF2 appeared to be expressed with NHERF1 in the dot-like structures." (PMID 29983887, 2018).
tauopathy (1 paper, 2023). Neurodegenerative disorders involving deposition of abnormal tau protein isoforms (tau proteins) in neurons and glial cells in the brain. "Moving into the Drosophila brain for mechanistic studies, we find a causal association between Moesin activation, filamentous actin formation, and cell cycle re-entry and that cellular hallmarks of EMT are present in Drosophila tauopathy." (PMID 36879821, 2023). "Our identification of Moesin as a hub gene in human and mouse tauopathy networks aligns with the findings of the consortia, and our studies in Drosophila provide the mechanistic insight into the consequences of Moesin activation in tauopathy that are critical for drug development." (PMID 36879821, 2023). "Based on the known role of Moesin as a driver of EMT, we became interested in the potential involvement of an EMT-like pathway in tauopathy." (PMID 36879821, 2023).
thymoma (1 paper, 2008). A neoplasm arising from the epithelial cells of the thymus. "The ezrin, radixin and moesin proteins, involved in intracellular anchoring of cell membrane proteins to the cytoskeleton, were detected by both the MG-thymoma MS samples and the exon arrays." (PMID 18545673, 2008). "MG-thymoma radixin median exonic change increased but ezrin and moesin decreased, reflecting specific regulation for each member of this protein family." (PMID 18545673, 2008).
thyroid tumours (1 paper, 2013). "In addition to our previous study, other authors found moesin between the differentially expressed proteins in thyroid tumours, and our ELISA assay confirmed the significant up-regulation of this protein not only in cPTC, but also in TcPTC." (PMID 24023790, 2013).
urothelial carcinoma (1 paper, 2020). A malignant neoplasm derived from the transitional epithelium of the urinary tract (urinary bladder, ureter, urethra, or renal pelvis). "Although the functional relevance of MSN has not been fully revealed in urothelial carcinoma, our in vitro 3D spheroid invasion assay along with the 2D invasion assay confirmed significantly decreased invasion ability in MSN-depleted BUC cell lines." (PMID 32326232, 2020).
tumor (106 papers, 2006 to 2026). "After conducting a literature search on the screened DEPs, we preliminarily identified moesin, which was a cytoskeleton regulatory protein that showed high expression in various tumor tissues or cells and was associated with tumor invasion or metastasis." (PMID 38267973, 2024). "In this study, highly abundant Ezrin (EZR), Talin-1 (TLN1), Adenylyl cyclase-associated protein 1 (CAP1), and Moesin (MSN) have been used as exosomal tumor biomarkers." (PMID 39001524, 2024). "The abnormalities of moesin, such as mislocalization, have been proved to be associated with tumor progression in multiple types of tumor." (PMID 37179366, 2023). "MSN has been linked to tumor growth, metastasis, invasion, and drug resistance in various types of cancer." (PMID 37446127, 2023). "Tissue microarray in sporadic and basal tumor showed that moesin was expressed in both conditions and was strongly associated with high proliferation rate, hormone receptor negativity, and had increased expression of myoepithelial markers." (PMID 33171868, 2020). "In line with the proposed signaling functions, we recently demonstrated that KLK4, in combination with KLK5, 6, and 7, regulates gene expression of other tumor-relevant genes such as MSN (encoding moesin), KRT7 and KRT19 (encoding keratins 7 and 19)." (PMID 30811511, 2019). "Importantly, the expression statuses of moesin and PD-L1 have been associated with poor prognosis, tumor malignancy, and metastasis in patients with uterine cervical SCC." (PMID 35807113, 2022). "However, although moesin has been found to make a difference in regulating immunity came from direct studies on immune cells, there is still no clear conclusion about what changes and mechanisms that moesin will cause for immune system in tumor cells." (PMID 33838692, 2021). "Mechanistically, APS upregulate miR-133a-3p, which suppresses its target gene MSN, thereby destabilizing PD-L1 and enhancing immune-mediated tumour cell killing." (PMID 40649307, 2025). "In conclusion, our study delineates the crucial role of MSN in TNBC tumor initiation and chemotherapy resistance, which is closely linked to the signaling cascade initiated by IL-6 binding to LPAR1." (PMID 40696387, 2025). "Bioluminescence imaging revealed that MSN knockdown significantly inhibited GSC‐driven tumor growth." (PMID 39921260, 2025). "A promoter assay also demonstrated that IL-6 promoter activity was highly enhanced in the group of MSN overexpression compared to the tumor cells with MSN depletion." (PMID 40696387, 2025). "The MCS exhibited improved viability and a gene expression profile associated with aggressive tumor characteristics, including increased expression of genes linked to cell survival and motility, such as COL1A1, MSN, HIF1A, TUBB, and ACTB." (PMID 41516217, 2025). "Moesin (MSN), a protein involved in cytoskeletal rearrangement, has been found to correlate with tumour progression in various cancers." (PMID 40649307, 2025). "Given MSN's essential function in GSCs, potentially facilitating aggressive expansion, we investigated the consequences of MSN disruption on GSC‐driven tumor growth in vivo." (PMID 39921260, 2025). "Western blotting of our cohorts (n = 15) also confirmed that there were approximately 6.5 higher levels of MSN protein expression in TNBC tissues compared to paired adjacent non-tumor breast parenchyma (p < 0.001)." (PMID 40696387, 2025). "Western blot analysis confirmed that ES treatment elevated the levels of Histone H4, Hspa8, MSN, Eef2, Aldoa, and Eno1, which is consistent with previous studies demonstrating Eno1’s tumor-suppressive function." (PMID 39940798, 2025). "Consistent with the in vitro and transcriptomic results, the orthotopic xenograft mouse models harboring MSN-knockdown tumors with the established 4T1/shMSN cell lines showed impaired tumor growth compared to the control mice." (PMID 40696387, 2025).
tumor (continued). "Using mass spectrometry-based proteomics analysis, we previously identified MSN as one of the tumor-suppressing proteins that were enriched in the tumor-suppressive CM38." (PMID 37699930, 2023). "By interacting with ezrin/radixin/moesin, S100P can promote trans-endothelial migration of tumor cells, thereby favoring metastasis." (PMID 37627239, 2023). "To investigate MSN’s tumor-promoting effect on CRC via RUNX2, we silenced RUNX2 expression in MSN-overexpressing cells by transfecting shRNA against RUNX2 (RUNX2-shRNA)." (PMID 37446127, 2023). "This study revealed the unconventional use of tumorigenic factors such as PABPC1, ENO1, and MSN as extracellular tumor-suppressing proteins, which were enriched in AMPK-inhibited PBMC/lymphocyte-derived CM." (PMID 36923539, 2023). "MSC CM was enriched with Moesin (MSN), which acted as an extracellular tumor-suppressing protein by interacting with CD44." (PMID 37699930, 2023). "NF2 (moesin–ezrin–radixin-like [MERLIN] tumor suppressor) is a member of the band 4.1 superfamily of proteins and is closely related to ezrin–radixin–moesin (ERM) proteins, which functions as links between the cell membrane and actin filaments." (PMID 37280085, 2023). "The tumor-suppressing actions of MSN and ENO1 were at least in part mediated by Metadherin (Mtdh), which is known to promote metastatic seeding." (PMID 36923539, 2023). "MSN expression by tumor cells is reported to be an unfavorable prognostic biomarker for oral cancer." (PMID 37056934, 2023). "Immunoblotting and IHC analysis of respective tumor samples showed efficient stabilization of Moesin upon depletion of FBXW2." (PMID 37736741, 2023). "In particular, in contrast to intracellular moesin, extracellular moesin exerts a tumor-suppressive effect by regulating cell adhesion through inhibition of Src and β-catenin signaling via its interaction with the CD44 extracellular domain and FN1." (PMID 37894408, 2023). "To elucidate the mechanism of the anti-tumor action of Hsp90ab1 and MSN, we evaluated their downstream protumorigenic genes such as TGFβ, Runx2, Snail, and MMP9, as well as PDL1 24 that inhibits immune responses and KDM3A 25 that regulates histone methylation." (PMID 34976221, 2022). "MSN protein expression was most abundant at tumor borders in the in vivo peritoneal tumors, especially where tumor cells interact with the surrounding tissue." (PMID 35927254, 2022). "Lastly, we observed herein that tumor-suppressive secretomes can be induced from tumor cells by the overexpression of Lrp5, MSN, and OPN." (PMID 34976221, 2022). "Hsp90ab1 and MSN are atypical tumor-suppressing proteins since they are multi-tasking, moonlighting proteins that promote tumorigenesis in tumor cells." (PMID 34976221, 2022). "Staining of patient peritoneal metastasis tissue confirmed the abundance of Moesin-positive tumor cells." (PMID 35927254, 2022). "Taken together, the result indicated the involvement of TGFβ via LAP-TGFβ, cell adhesion via CD44, and extracellular matrix via FN1 in the anti-tumor action of extracellular Hsp90ab1 and MSN." (PMID 34976221, 2022). "We next examined the mechanism of the action of OPN by focusing on Hsp90ab1 and MSN, two atypical tumor-suppressing proteins." (PMID 34976221, 2022). "ICAM-3 is an adhesion molecule that can interact with LFA-1 extracellularly or ezrin/radixin/moesin intracellularly, contributing to tumor metastasis." (PMID 36059515, 2022). "While Lrp5 CM, mostly analyzed in this study, contains a spectrum of secretomes, we focused on the role of three moonlighting proteins, OPN, Hsp90ab1, and MSN, for tumor suppression." (PMID 34976221, 2022). "To assess the potential mechanism of tumor-suppressive action of Hsp90ab1 and MSN, we conducted an immunoprecipitation assay." (PMID 34976221, 2022). "Both IHC and IF staining results showed that the expression of CD31, RhoJ, EpCAM, and moesin were significantly increased in tumor tissues derived from the RhoJ-overexpressing group." (PMID 35173528, 2022).